C11orf52 (chromosome 11 open reading frame 52)
Synonyms: MGC14839; FLJ25219
Tractability: PROTAC: its protein half-life has been measured.
Gene: Protein-coding gene on chromosome 11 (111,918,032 to 111,926,871, forward strand). Ensembl gene ENSG00000149300.
Subcellular location (Human Protein Atlas): Cell Junctions
Gene Ontology:
Molecular function: protein binding
Cellular component: cell junction; extracellular exosome
Genetic constraint (gnomAD): Loss-of-function variants: 5 observed, 10.37 expected, observed/expected ratio (o/e) 0.48, 90% interval 0.25 to 1.01. The upper end of that interval is the gene's LOEUF score, 1.01, which puts it in group 4 of 6, group 1 being the genes least tolerant of losing a copy. Missense variants: 128 observed, 153.16 expected, observed/expected ratio (o/e) 0.84, 90% interval 0.72 to 0.97. Synonymous variants: 49 observed, 56.96 expected, observed/expected ratio (o/e) 0.86, 90% interval 0.68 to 1.09.
Homologues: Orthologues: chimpanzee C11H11orf52 (99% identical), macaque C14H11orf52 (92% identical), rabbit C11orf52 (76% identical), dog C11orf52 (72% identical), pig C11orf52 (71% identical), mouse 2310030G06Rik (63% identical), rat Hspb2 (41% identical).
Diseases named in the same sentence as C11orf52 in open-access papers:
C11orf52 is named in the same sentence as 4 diseases in open-access papers, as found by Europe PMC text mining. Sharing a sentence is not in itself a finding about the gene and the disease. The quoted sentences say what the papers report.
bladder cancer (1 paper, 2023). "Furthermore, an uncharacterized protein C11orf52 (C11orf52) was under-expressed in the sEV fractions of the bladder cancer patients." (PMID 37371512, 2023). "Additionally, three proteins were under-expressed in samples of bladder cancer patients in this study: human leukocyte antigen class II histocompatibility antigen alpha chain (HLA-DMA), Na(+)/H(+) exchange regulatory cofactor 1 (NHE-RF1, SLC9A3R1) and uncharacterized protein C11orf52 (C11orf52)." (PMID 37371512, 2023).
C11orf52 also shares sentences with these, for which no sentence is quoted: colorectal cancer (1 paper); non-small cell lung carcinoma (1); tumor (1).